SGIP1 (SH3GL interacting endocytic adaptor 1)
Description:
May function in clathrin-mediated endocytosis. Has both a membrane binding/tubulating activity and the ability to recruit proteins essential to the formation of functional clathrin-coated pits. Has a preference for membranes enriched in phosphatidylserine and phosphoinositides and is required for the endocytosis of the transferrin receptor. May also bind tubulin. May play a role in the regulation of energy homeostasis.
Synonyms: DKFZp761D221
Tractability: Antibody: UniProt places it where antibodies can reach, with high confidence; its Gene Ontology location is reachable by antibodies, with high confidence. PROTAC: its protein half-life has been measured.
Gene: Protein-coding gene on chromosome 1 (66,533,267 to 66,751,139, forward strand). Ensembl gene ENSG00000118473.
Subcellular location: Membrane, clathrin-coated pit
Subcellular location (Human Protein Atlas): Mitochondria
Pathways (Reactome):
Vesicle-mediated transport: Cargo recognition for clathrin-mediated endocytosis; Clathrin-mediated endocytosis
Gene Ontology:
Molecular function: protein binding; SH3 domain binding; microtubule binding; phospholipid binding
Biological process: energy homeostasis; positive regulation of feeding behavior; positive regulation of receptor-mediated endocytosis; response to dietary excess; clathrin-dependent endocytosis
Cellular component: clathrin-coated pit; cytoplasm; plasma membrane; AP-2 adaptor complex; clathrin-coated vesicle; cytosol
Genetic constraint (gnomAD): Loss-of-function variants: 27 observed, 86.41 expected, observed/expected ratio (o/e) 0.31, 90% interval 0.23 to 0.43. The upper end of that interval is the gene's LOEUF score, 0.43, which puts it in group 1 of 6, group 1 being the genes least tolerant of losing a copy. Missense variants: 846 observed, 974.06 expected, observed/expected ratio (o/e) 0.87, 90% interval 0.82 to 0.92. Synonymous variants: 339 observed, 356.9 expected, observed/expected ratio (o/e) 0.95, 90% interval 0.87 to 1.04.
Homologues: Orthologues: macaque SGIP1 (99% identical), pig SGIP1 (97% identical), chimpanzee SGIP1 (97% identical), dog SGIP1 (96% identical), rat Sgip1 (96% identical), mouse Sgip1 (95% identical), guinea pig SGIP1 (93% identical), rabbit SGIP1 (93% identical), tropical clawed frog sgip1 (77% identical), zebrafish sgip1a (66% identical), zebrafish sgip1b (48% identical), Drosophila melanogaster CG8176 (25% identical), and 1 more. Paralogues in human: FCHO2 (38% identical), FCHO1 (29% identical), PSTPIP1 (6% identical), PSTPIP2 (4% identical), GAS7 (3% identical).
Diseases named in the same sentence as SGIP1 in open-access papers:
SGIP1 is named in the same sentence as 18 diseases in open-access papers, as found by Europe PMC text mining. Sharing a sentence is not in itself a finding about the gene and the disease. The quoted sentences say what the papers report.
Obesity (8 papers, 2016 to 2023). Accumulation of substantial excess body fat. "Elevated levels of SGIP1 mRNA in the hypothalamus of the Israeli sand rat (Psammomys obesus) correlate with obesity of the animals held in captivity, and genetic variations within the SGIP1 gene are associated with energy balance disturbances in humans." (PMID 33491188, 2021). "In line with this, SGIP1 was associated with measures of obesity such as fat mass in humans." (PMID 31671891, 2019). "SGIP1 mRNA levels are increased in the hypothalamus of the Israeli sand rat (Psammomys obesus), where they correlate with obesity of captive animals." (PMID 37547151, 2023). "SGIP1 overproduction in the hypothalamus of the Israeli sand rat leads to obesity and metabolic syndrome, if the animals are kept in captivity with food ad libitum." (PMID 37547151, 2023). "After being viewed as a candidate gene for energy homeostasis and a determinant of obesity-related traits, SGIP1 was identified as an ortholog of FCHo1/2 and thus was thought to play a role in CME." (PMID 35004694, 2021). "Both SGIP1 and CB1R are strongly associated with diet-induced obesity [DIO;] and siRNA-mediated knockdown of hypothalamic SGIP1 inhibited food intake, suggesting that SGIP1 in the hypothalamus plays a role in energy expenditure." (PMID 32595453, 2020). "SGIP1 was first identified as a novel transcript in a screen of hypothalamic mRNA in the obesity model of the fat sand rat (Psammomys obesus) that is markedly upregulated in comparison to lean counterparts." (PMID 32595453, 2020). "SGIP1 was initially identified in a screen for central nervous system regulators of energy balance and obesity, and it was found upregulated in the hypothalamus of an obese mouse line." (PMID 31671891, 2019). "SGIP1 has been found as a potential therapeutic target for obesity- and diabetes-related symptoms, since the selective reduction of the expression of SGIP1 consequenced with inhibition of food intake and the decrement of body weight in rat models." (PMID 31244774, 2019). "On the other hand, genetic deletion of SGIP1 did not affect body weight implying that only overexpression of SGIP1 in the hypothalamus is associated with obesity." (PMID 33491188, 2021). "Interestingly, SGIP1 deletion did not decrease body weight; thus, it appears that only upregulation of hypothalamic SGIP1 is associated with obesity." (PMID 37547151, 2023).
Anxiety (3 papers, 2021 to 2024). Intense feelings of nervousness, tension, or panic often arise in response to interpersonal stresses. "Based on our results, we would conclude that SGIP1 can regulate anxiety levels under specific contexts, possibly via modulation of CB1 receptor signalling." (PMID 33491188, 2021). "For the current study, we developed mice with constitutively deleted SGIP1 for behavioural studies, assessing anxiety‐related behaviour, coping with unescapable situations, and we tested their acute nociception." (PMID 33491188, 2021). "Sgip1 knockdown mice show decreased anxiety, enhanced fear extinction, and reduced nociception." (PMID 38263132, 2024). "Increasing anandamide levels via pharmacological inhibition of its degrading enzyme, fatty acid amide hydrolase (FAAH), or genetic deletion of FAAH elicits phenotypes that are prominent for decreased anxiety-like behavior, as we observed in our evaluation of SGIP1−/− mice." (PMID 37547151, 2023). "Increasing anandamide levels via chemical inhibition of its catabolic enzyme fatty acid amide hydrolase (FAAH) or the deletion of FAAH resulted in phenotypes with behavioural aberrations including decreased anxiety‐like behaviour, as we observed in the present tests with SGIP1−/− mice." (PMID 33491188, 2021). "Because of these actions, SGIP1 may modulate affect, anxiety, pain processing, and other physiological processes controlled by the endocannabinoid system (ECS)." (PMID 33491188, 2021).
Depression (2 papers, 2025). "Depression also causes bone loss and reduced bone density, which may share genetic factors with fractures, such as SGIP1, significantly increasing the risk of fractures." (PMID 39937768, 2025). "Additionally, some depression-associated genes in the South Asian population are linked to diet and metabolism, such as FADS1, FADS2, LPIN3, and SGIP1." (PMID 40075226, 2025).
Parkinsonism (2 papers, 2024 to 2025). Characteristic neurologic anomaly resulting from degeneration of dopamine-generating cells in the substantia nigra, a region of the midbrain, characterized clinically by shaking, rigidity, slowness of movement and difficulty with walking and gait. "SNP rs7549881, near SGIP1 at 1p31.3, is significantly associated with digestive disorders and Parkinsonism in women." (PMID 40979778, 2025). "Variants in SGIP1 can disrupt these processes, leading to synaptic dysfunction, which has been linked to neurodegenerative diseases such as early-onset Parkinsonism." (PMID 40979778, 2025). "SGIP1 (SH3GL Interacting Endocytic Adaptor 1) at 1p31.3 has been implicated in early-onset Parkinsonism in a rare familial case." (PMID 40979778, 2025). "It will, nonetheless, be essential to verify the presence of SGIP1 variants in additional cases of familial parkinsonism to provide definite proof of causality to disease." (PMID 39332416, 2024). "We have identified a candidate causative mutation in synaptic “SH3GL2 Interacting Protein 1” (SGIP1), linked to early-onset parkinsonism in a consanguineous Arab family." (PMID 39332416, 2024). "We present the identification of a loss-of-function variant in SGIP1 as a plausible candidate gene to cause recessive parkinsonism." (PMID 39332416, 2024). "identify a mutation in SGIP1 putatively linked to early-onset parkinsonism in an Arab family." (PMID 39332416, 2024). "Hence, SGIP1, like other early-onset Parkinson’s proteins, is associated with functions that regulate synaptic proteostasis." (PMID 39332416, 2024). "Additional studies will now be required to unravel the potential convergent mechanistic pathways between SGIP1 and these other synaptic proteins related to Parkinson’s disease." (PMID 39332416, 2024). "The SGIP1 gene had not been previously associated with Parkinsonism, a group of disorders characterized by motor dysfunction and cognitive decline, including Parkinson’s disease (PD)." (PMID 40979778, 2025).
colorectal cancer (1 paper, 2019). A primary or metastatic malignant neoplasm that affects the colon or rectum. "Hypomethylation and retrotransposition of SGIP1 have been reported in colorectal cancer samples." (PMID 31244774, 2019).
gastric cancer (1 paper, 2019). A primary or metastatic malignant neoplasm involving the stomach. "The expression level of SGIP1 has been shown significantly decreased in gastric cancer when compared to control samples." (PMID 31244774, 2019).
neuroblastoma (1 paper, 2014). Neuroblastoma (NB) is the most common solid, extracranial childhood tumor. "Indeed, SGIP1 is essentially a neuronally-expressed protein, with RT-PCR and RNA-seq indicating >30-fold higher transcript abundance in SH-SY5Y neuroblastoma cells vs HeLa cells." (PMID 25303365, 2014).
rectal cancer (1 paper, 2019). A primary or metastatic malignant neoplasm that affects the rectum. "SGIP1 has been identified as the second most significantly upregulated gene in the colon and rectal cancers samples." (PMID 31244774, 2019).
thyroid (1 paper, 2026). "Co-expression analysis suggests interactions between SGIP1 and SLC26A4, implicating diverse pathways in thyroid carcinogenesis and informing precision medicine strategies." (PMID 42306204, 2026).
neurodevelopmental disorder (1 paper, 2025). A behavioral and cognitive disorder with onset during the developmental period that involves impaired or aberrant development of intellectual, motor, or social functions. "Beyond neurodegeneration, abnormalities in endocytic processes involving SGIP1 can also affect neuronal development and connectivity, suggesting a possible role in neurodevelopmental disorders." (PMID 40979778, 2025).
neurological diseases (1 paper, 2025). "Ongoing research continues to investigate its broader implications in neurological diseases and how targeting SGIP1 pathways might offer new therapeutic strategies." (PMID 40979778, 2025).
psychiatric disorder (1 paper, 2018). A disorder characterized by behavioral and/or psychological abnormalities, often accompanied by physical symptoms. "A number of the identified genes such as ACAT1 and SGIP1 confer risk for diseases or endophenotypes that are predominantly specific to the human species, such as complex psychiatric disorders." (PMID 30373661, 2018).
SGIP1 also shares sentences with these, for which no sentence is quoted: diabetes (2 papers); cancer (1); glioblastoma (1); metabolic syndrome (1); Stroke (1); tumor (1).